ITGAV (integrin subunit alpha V)
Diseases named in the same sentence as ITGAV in open-access papers (continued):
Sharing a sentence is not in itself a finding about the gene and the disease.
sarcoma (3 papers, 2022 to 2025). A usually aggressive malignant neoplasm of the soft tissue or bone. "The effect of ITGB3 or ITGAV shRNA on cell migration and invasion was analyzed using Boyden chamber assays, in which cells were seeded onto a porous membrane that was either uncoated or coated with Matrigel, a sarcoma-derived basement membrane preparation." (PMID 40662366, 2025).
Sepsis (3 papers, 2016 to 2024). Sepsis is defined as life-threatening organ dysfunction caused by a dysregulated host response to infection. "Of the ICU Day-3 classifying proteins, ST2, CNTN5, and ITGAV decreased significantly in median level from ICU Day-1 to Day-3 and VSIG4 increased significantly in sepsis patient plasma between Day-1 and Day-3." (PMID 36572854, 2022).
adrenocortical carcinoma (2 papers, 2022 to 2025). "The analysis revealed significant correlations between ITGAV expression and PFS in several cancers, including adrenocortical carcinoma (ACC), GBM, KIRC, KIRP, LGG, LIHC, PAAD, STAD, and UCEC." (PMID 40775249, 2025).
astrocytoma (2 papers, 2020 to 2025). "ITGAV and ITGB5 expression was also elevated in astrocytomas." (PMID 40281508, 2025).
autoimmune disease (2 papers, 2022 to 2024). A disorder resulting from loss of function or tissue destruction of an organ or multiple organs, arising from humoral or cellular immune responses of the individual to their own tissue constituents. "Moreover, ITGAV is associated with the occurrence and development of multiple diseases, particularly cancer and autoimmune diseases." (PMID 39581873, 2024). "Based on the diverse systems biology and functional annotations of the 7 query genes, ITGAV, FN1, and HLA-DQB1 were prominent in autoimmune diseases." (PMID 35692981, 2022).
endometriosis (2 papers, 2020). The growth of functional endometrial tissue in anatomic sites outside the uterine body. "ITGAV is an integrin, that mediates binding to fibronectin, vitronectin, fibrinogen and is upregulated in women with endometriosis when compared to healthy women during menstruation." (PMID 32824678, 2020).
esophageal squamous cell carcinoma (2 papers, 2024 to 2025). Esophageal squamous cell carcinoma (ESCC) is a type of esophageal carcinoma (EC) that can affect any part of the esophagus, but is usually located in the upper or middle third. "Indomethacin, for instance, diminishes the growth and recurrence of esophageal squamous cell carcinoma (ESCC) by enhancing the E3 ligase synovial apoptosis inhibitor 1 (SYVN1)-mediated ubiquitination of integrin αv (ITGAV)." (PMID 39048965, 2024). "It had been reported that ITGAV was a promising therapeutic target for esophageal squamous cell carcinoma (ESCC), as indomethacin can inhibit ESCC growth by binding to ITGAV, promoting SYVN1-mediated ubiquitination of ITGAV, and enhancing cytotoxic CD8+ T cell responses." (PMID 40018050, 2025).
gastritis (2 papers, 2024 to 2025). Inflammation of the stomach. "In turn, ANGPTL4 induced Treg proliferation by binding to ITGAV to activate PI3K–AKT–NF-κB, promoting H. pylori-associated gastritis." (PMID 39022746, 2024).
kidney cancer (2 papers, 2024 to 2025). Primary or metastatic malignant neoplasm involving the kidney. "Our findings further underscore that ITGAV expression is notably increased in COAD, LIHC, and PAAD, whereas it is significantly downregulated in kidney cancer tissues." (PMID 40775249, 2025).
meningioma (2 papers, 2020). A generally slow growing tumor attached to the dura mater. "Our study identified integrin beta 3 precursor (ITGB3), alpha V integrin (ITGAV) and alpha M integrin (ITGAM) only in male meningioma samples; these proteins are associated with meningiomas tumorigenesis 7,8." (PMID 32587372, 2020). "The global proteomic analysis of meningioma patients in the current study revealed perturbations in several components of Integrin including ITGAV, ITGB2, ITGA2B, and ILKAP." (PMID 32974197, 2020).
metastatic disease (2 papers, 2020 to 2023). "On the other hand, clonal mutations in ARNT (OVA_047), NTRK1 (OVA_048), MYH9 (OVA_047) and PPARG (OVA_047), and subclonal mutations in ITGAV (OVA_047) and PTPRT (OVA_003) were all specific to metastatic tumours." (PMID 32099096, 2020).
osteoarthritis (2 papers, 2012 to 2023). A noninflammatory degenerative joint disease occurring chiefly in older persons, characterized by degeneration of the articular cartilage, hypertrophy of bone at the margins and changes in the synovial membrane. "Interestingly, ITGAV, ITGB1, and ITGA10 involve multiple chondrocyte subtypes, which suggests that they have a greater impact on the development of osteoarthritis." (PMID 37660146, 2023).
ovarian serous cystadenocarcinoma (2 papers, 2022 to 2025). A malignant serous cystic epithelial neoplasm arising from the ovary. "Positive correlations have been found between the gene expression of integrin αV (ITGAV) and PD-L1 (CD274) or CD44 in ovarian serous cystadenocarcinoma from the OncoDB online database." (PMID 40093794, 2025). "Amongst the proteomics identified and validated genes, the expression of TGFBI significantly positively correlated with the expression of GFPT2, FLNA, G6PD, ITGAV, ITGA1 and ITGA2 within the serous ovarian cystadenocarcinomas in TIMER database." (PMID 36463238, 2022).
pancreatic ductal adenocarcinoma (2 papers, 2021 to 2025). An infiltrating adenocarcinoma that arises from the epithelial cells of the pancreas. "In the present study, we could show that ITGAV expression was upregulated in intraperitoneal pancreatic ductal adenocarcinoma xenograft tumor cells that grew under selectin-deficient conditions, suggesting a compensatory increase in integrin expression." (PMID 34174926, 2021). "In SMAD4‐positive pancreatic ductal adenocarcinoma (PDAC), integrin subunit alpha V (ITGAV) activates latent TGF‐β, which binds to the TGF‐β receptor and phosphorylates SMAD2/3." (PMID 40739706, 2025).
renal carcinoma (2 papers, 2019 to 2026). A carcinoma arising from the epithelium of the renal parenchyma or the renal pelvis. "Some of these genes belong to pathways known to be dysregulated in renal cancer (e.g., ITGAV, TIAM1, and PIK3CB)." (PMID 30942869, 2019).
rheumatoid arthritis (2 papers, 2007 to 2014). A chronic, systemic autoimmune disorder characterized by inflammation in the synovial membranes and articular surfaces. "ITGAV polymorphisms are associated with a number of conditions including rheumatoid arthritis, chronic hepatitis B virus infection, and primary biliary cirrhosis." (PMID 24886251, 2014). "Hyperangiogenesis is involved in rheumatoid arthritis (RA) and the ITGAV gene is located in 2q31, one of the suggested RA susceptibility loci." (PMID 17615072, 2007).
serous ovarian cancer (2 papers, 2021 to 2022). "The upregulation of G6PD, AKR1B1, ITGAV, and TGFβ1 in OVCAR5 CBPR cells was also identified in the tumors of platinum-resistant compared to platinum-sensitive high grade serous ovarian cancer (HGSOC) patients." (PMID 36463238, 2022). "Accordingly, we observed significantly higher expression levels of ITGAV and ITGB3 in human high-grade serous ovarian cancer specimens and ITGAV correlated positively with Wnt5A in metastatic serous type ovarian cancer." (PMID 33723319, 2021).
skin carcinoma (2 papers, 2018 to 2024). "Tissue microarray data showed that ITGAV expression was elevated in skin cancer tissues from patients." (PMID 30486830, 2018). "The combination of IL-32γ and NF-κB inhibitor, BAY, synergistically reduced TPA-induced epidermal hyperplasia, inflammation, and skin cancer sphere formation by further suppressing ITGAV and TIMP-1." (PMID 30486830, 2018). "In this study, the expression of IL-32γ resulted in reduced skin tumor development by downregulating ITGAV and TIMP-1 expression through the regulation of NF-κB signaling in IL-32γ mice." (PMID 30486830, 2018). "This study demonstrated the inhibitory effect of IL-32γ on skin tumor development by the downregulation of ITGAV and TIMP-1 via the NF-κB signaling." (PMID 30486830, 2018). "We analyzed the expressions levels of IL-32γ, nuclear p65 and ITGAV in patient skin tumor tissues at different stages by immunohistochemical staining analysis." (PMID 30486830, 2018). "In GWAS analysis, we found that ITGAV and TIMP-1 were significantly associated with IL-32γ-inhibited skin tumor development." (PMID 30486830, 2018). "Knockout of ITGAV in mice seemed to promote skin cancer development." (PMID 30486830, 2018). "With the data analysis using a genome-wide association study (GWAS), we found that IL-32 was closely related to many cancers, and further analysis showed that IL-32 was closely associated with several genes including ITGAV and TIMP-1, which have been implicated in skin tumor development." (PMID 30486830, 2018). "These facts correlated with our results revealing that IL-32γ suppressed cancer stemness through the inhibition of ITGAV and TIMP-1 in A431 and SK-Mel-28 skin cancer cells." (PMID 30486830, 2018). "The expression levels of CD44 and CD133 were decreased by knockdown of ITGAV and TIMP-1 in skin cancer cells compared to control cells." (PMID 30486830, 2018). "However, the expression of nuclear translocation of p65 and ITGAV were increased in the late stage skin tumors compared to normal tissues." (PMID 30486830, 2018).
Aortic root aneurysm (1 paper, 2020). An abnormal localized widening (dilatation) of the aortic root. "ITGAV protein levels were also increased in aortic root aneurysm tissue from MFS patients compared to normal control (MFS 4.8 vs. control 2.5-fold aortic root/ascending)." (PMID 33230159, 2020).
asthma (1 paper, 2023). "Our results suggest that the αvβ3-mediated T-T cell interactions may also contribute to the roles of αvβ3 in human disease, and that human ITGB3 and ITGAV may represent potential therapeutic targets in asthma." (PMID 36550322, 2023).
benign ovarian tumors (1 paper, 2020). "Using LASSO regression, a multiplex model including 6 biomarkers (HE4, CA125, ITGAV, CXCL1, CEACAM1, IL-10RB) and age had the highest diagnostic accuracy for discrimination between benign ovarian tumors and EOC including borderline tumors." (PMID 33075095, 2020).
benign prostate hyperplasia (1 paper, 2020). "Materials and Methods: Urinary ITGAV expression was determined by Western blot analysis and quantified by ELISA in urine from men with PCa (n = 47), benign prostate hyperplasia (n = 42) and age-matched controls (n = 22)." (PMID 33791193, 2020).
chordoma (1 paper, 2023). Chordomas are rare malignant tumors arising from embryonic remnants of the notochord in axial skeleton. "Interestingly, in recurrent chordomas, interactions involving FN1 and ITGAV/ITGB1, as well as FN1 and ITGA3/ITGB1, emerged as significant contributors to this communication network." (PMID 37784253, 2023).
Cognitive impairment (1 paper, 2026). Abnormal cognition is characterized by deficits in thinking, reasoning, or remembering. "Of the top 10 most significant proteins, six (PLOD1, MFN2, NGFR, PPP2R5E, C4A/C4B, and ITGAV) have previously been linked to AD and/or cognitive function, underscoring their potential as biomarkers of cognitive impairment." (PMID 42253369, 2026).
COVID-19 (1 paper, 2021). A disease caused by infection with severe acute respiratory syndrome coronavirus 2. "All genes (PPARG, CD36, STAB1, ITGAV, and ANXA2) downregulated in surviving patients with COVID-19 are related to cholesterol homeostasis." (PMID 34944005, 2021).
cutaneous squamous cell carcinoma (1 paper, 2025). "It had been demonstrated that ITGAV was a prognostic biomarker of relapse in cutaneous squamous cell carcinomas (cSCCs) that would allow improved patient stratification." (PMID 40018050, 2025).
diabetic cardiomyopathy (1 paper, 2022). Diabetic cardiomyopathy is a disorder of the heart muscle in people with diabetes. "The members of integrin family, especially ITGAV and ITGB5, are potential receptors of irisin in osteocytes and fat cells, and simultaneous knockdown of ITGAV and ITGB5 also blocked FNDC5‐mediated protective effects against diabetic cardiomyopathy." (PMID 35166002, 2022).
emphysema (1 paper, 2008). "Our results have supported neither ITGB6 nor ITGAV as candidate genes for juvenile hairlessness and age dependent emphysema in pigs." (PMID 18549483, 2008).
endometrial cancer (1 paper, 2021). Primary or metastatic malignant neoplasm involving the endometrium (mucous membrane that lines the endometrial cavity). "In addition, a positive correlation was found between the expression of NUCB2/NESF-1 and EMT-related genes such as desmoplakin (DSP), Integrin Subunit Alpha V (ITGAV), metalloproteinase 3 (MMP3), tetraspanin 13 ( TSPAN13), and Cadherin 2 (CDH2) in endometrial cancer cells." (PMID 34361082, 2021).
gout (1 paper, 2023). A condition characterized by painful swelling of the joints, which is caused by deposition of urate crystals. "As a first exploration, mRNA levels of TGFB1, TGFBRI, TGFBRII and three TGF-β target genes ITGAV, MMP9 and SMAD7 were compared between untreated adherent monocytes of patients with gout and age and sex matched healthy controls." (PMID 36850003, 2023). "Also, the expression of the downstream targets ITGAV and MMP9 were increased in gout patients." (PMID 36850003, 2023).
heart failure (1 paper, 2016). Inability of the heart to pump blood at an adequate rate to meet tissue metabolic requirements. "Induction of both ItgaV (integrin alpha v), and Angptl4 are in response to heart dysfunction and heart failure as these proteins play vital roles in myocardial functions." (PMID 27548259, 2016).
low grade glioma (1 paper, 2019). A grade I or grade II glioma arising from the central nervous system. "CD155 can form the same complex with CD96, CD226, AFDN, ITGAV, ITGB3, and AFDN in low-grade glioma (LGG) and GBM samples derived from the Biological Pathway Ex-change (BioPAX)." (PMID 31377744, 2019).
metastatic prostate carcinoma (1 paper, 2021). A carcinoma that arises from the prostate gland and has spread to other anatomic sites. "Among the eight integrin subunits analyzed, ITGA5, ITGAV, ITGB1, ITGB3, ITGB4, and ITGB5 were upregulated in the bone compared with the other organs, suggesting that some integrins may confer osteotropic properties on metastatic prostate cancer." (PMID 33514011, 2021).
neuroblastoma (1 paper, 2022). Neuroblastoma (NB) is the most common solid, extracranial childhood tumor. "Moreover, the neuroblastoma mesenchymal transcriptional signature, repressed after BAF disruption, is determined by a specific super-enhancer configuration, and many of these genes (LOXL2, SNAI2, CDH11, ITGAV) are associated with chromatin repressive events." (PMID 36057593, 2022).
Nivelon-Nivelon-Mabille Syndrome (1 paper, 2022). "Of these, four genes were determined to be related to bone development (PLXNA2 with prognathism, HHAT with the complex Nivelon-Nivelon-Mabille Syndrome, MBOAT2 with chondrocyte differentiation, and ITGAV with chondrodystrophy), and one to calcium homeostasis (HPCAL1)." (PMID 36230363, 2022).
oncocytomas (1 paper, 2020). "Two proteins—LAMP1 and ITGAV—were selected for verification in an independent cohort of oncocytomas and chRCC, with ITGAV1 expression to exhibit strong staining in oncocytomas, whereas LAMP1 staining was robustly detected in chRCC." (PMID 32742246, 2020).
oral squamous cell carcinoma (1 paper, 2021). "Similarly, in oral squamous cell carcinoma, overexpression of ITGAV is reported to activate MEK/ERK signaling pathways promoting proliferation and invasion." (PMID 34680783, 2021).
osteoporosis (1 paper, 2022). A condition of reduced bone mass, with decreased cortical thickness and a decrease in the number and size of the trabeculae of cancellous bone (but normal chemical composition), resulting in increased fracture incidence. "The last gene implicated in bone development, ITGAV, encodes the integrin subunit alpha V, a protein that is involved in osteoporosis, among other processes." (PMID 36230363, 2022).
ovarian disease (1 paper, 2021). "In addition, four ovarian DEGs (ABCA5, ADIPOQ, ITGAV, and PPARG) in the FM_1-vs-NM_1 group are associated with negative regulation of macrophage-derived foam cell differentiation and are all involved in ovarian disease." (PMID 35052428, 2021).
pulmonary fibrosis (1 paper, 2022). Chronic progressive interstitial lung disorder characterized by the replacement of the lung tissue by connective tissue, leading to progressive dyspnea, respiratory failure, or right heart failure. "From those only two had fibrotic indications, STX-100 targeting ITGAV and Pamrevlumab targeting CCN2, both for pulmonary fibrosis indications." (PMID 36531712, 2022).
renal tumors (1 paper, 2018). "We present one of the first differential proteome profiling studies on ROs and chRCCs and highlight differential abundance of LAMP1 and ITGAV in these renal tumors." (PMID 30087584, 2018).
scleroderma (1 paper, 2023). Scleroderma is a rare autoimmune connective tissue disorder characterized by abnormal hardening of the skin and, sometimes, other organs. "ADSCs also expressed FNDC5, a fibronectin, which interacted with ITGB5 and additionally with ITGAV in scleroderma." (PMID 37443817, 2023). "ADSCs also expressed fibronectin type III domain-containing protein 5 (FNDC5), which interacted with ITGB5 and additionally with ITGAV in scleroderma on various subclusters." (PMID 37443817, 2023). "Integrin subunit alpha V (ITGAV) and caveolin 1 (CAV1) interactions were specific to scleroderma fibroblasts." (PMID 37443817, 2023). "ITGAV and CAV1 interactions were only among the top interactions in scleroderma fibroblasts." (PMID 37443817, 2023).
testicular cancer (1 paper, 2024). A primary or metastatic malignant neoplasm that affects the testis. "The SNP rs3213964 at ITGAV gene is evident through cross validation approach to be associated with male-related phenotypic traits such as malignant neoplasm of testis, sitting height and self-reported testicular cancer which supports the stronger associations detected in males." (PMID 38326779, 2024).
thrombosis (1 paper, 2025). "In the current study, COL5A1, VCAN, PTGS2, ITGAV and ITGA8 were five hub genes revealed to be closed associated with thrombosis-prone plaques." (PMID 41415585, 2025). "Among them, COL5A1, VCAN, PTGS2, and ITGAV showed extremely significant increases (P < 0.01); ITGA8 was significantly decreased in the plaque group and thrombosis group (P < 0.01)." (PMID 41415585, 2025).
thyroid tumor (1 paper, 2024). A benign or malignant neoplasm affecting the thyroid gland. "We then performed a bioinformatic analysis with the cBioPortal program in patients with different types of cancer we verified the existence of the genes ITGAV and ITGB3 (mTR) and found that thyroid tumors are the ones with the highest αv and β3 integrin expression." (PMID 39596225, 2024).
ZIKV infection (1 paper, 2020). "We also analysed the potential role of putative miR-142-5p target genes, IL6ST and ITGAV, during ZIKV infection." (PMID 32902370, 2020). "Interestingly, miR-142-5p was significantly downregulated upon ZIKV infection, whereas cellular targets of miR-142-5p, IL6ST and ITGAV, were upregulated." (PMID 32902370, 2020).